COL6A4P1 (collagen type VI alpha 4 pseudogene 1)
Synonyms: VWA6; DIVA; COL6A4; COL6A4P; formerly DVWA
Gene: Transcribed unprocessed pseudogene on chromosome 3 (15,151,833 to 15,180,961, reverse strand). Ensembl gene ENSG00000230524.
Diseases named in the same sentence as COL6A4P1 in open-access papers:
COL6A4P1 is named in the same sentence as 1 disease in open-access papers, as found by Europe PMC text mining. Sharing a sentence is not in itself a finding about the gene and the disease.
COL6A4P1 shares sentences with these, for which no sentence is quoted: tumours (1 paper).